CCK (cholecystokinin)
Diseases named in the same sentence as CCK in open-access papers (continued):
Sharing a sentence is not in itself a finding about the gene and the disease.
acute pancreatitis (45 papers, 2012 to 2026). An acute inflammatory process that leads to necrosis of the pancreatic parenchyma. "Like CCK, this CCK analogue stimulates, among other things, secretion of digestive enzymes by the pancreas and is therefore widely used to cause and model acute pancreatitis in mice." (PMID 34572737, 2021). "Supraphysiological concentrations of cholecystokinin (CCK) cause intrapancreatic zymogen activation and acute pancreatitis." (PMID 32293245, 2020). "Acute pancreatitis was induced through consecutive IP injections of caerulein, a cholecystokinin (CCK) analog that causes activation of digestive enzymes in the pancreatic epithelium resulting in inflammation, edema, and cell death." (PMID 23383154, 2013). "Also of note, transgenic HLA-DQ8 mice, grown in germ-free conditions and fed a gluten-free diet, developed acute pancreatitis after intra-peritoneal injection of cerulein, a cholecystokinin analogue that causes hyperstimulation of the exocrine component." (PMID 30149525, 2018). "The possible importance of group I PAKs in acute pancreatitis is further supported by a recent study in mice using an in vivo supramaximal CCK model of acute pancreatitis." (PMID 40001881, 2025). "These organelles develop in acinar cells exposed to several inducers of acute pancreatitis (including taurolithocholic acid and high concentrations of secretagogues cholecystokinin and acetylcholine)." (PMID 36010591, 2022). "Murine models of acute pancreatitis, using both isolated cells and in vivo preparations and treatments with cholecystokinin orthologue, cerulein, are often used for preclinical studies." (PMID 34440775, 2021). "In the cholecystokinin (CCK)-induced acute pancreatitis model, EA at ST36 reduced β-amylase and lipase levels in serum, which significantly rise with the symptoms of acute pancreatitis." (PMID 35095910, 2021). "Cerulein, a cholecystokinin analog, induces calcium (Ca2+) overload, oxidative stress, and IL-6 expression in pancreatic acinar cells, which are hallmarks of acute pancreatitis." (PMID 34349610, 2021). "These enhance the effects of cholecystokinin (CCK) on NF-κB activation and in vivo, in combination with bacterial LPS, can result in acute pancreatitis, atrophy and activation of PSCs." (PMID 34572737, 2021). "Elevated plasma CCK concentrations were observed in patients as well as in various animal models of acute pancreatitis." (PMID 32617135, 2020). "An inducer of acute pancreatitis taurolithocholic acid 3‐sulphate and supramaximal concentrations of cholecystokinin triggered the formation of giant (more than 2.5 μm in diameter) endocytic vacuoles." (PMID 29717784, 2018). "Cerulein, a cholecystokinin analog, induces intra-acinar activation of trypsinogen in the pancreas, which results in human acute pancreatitis-like symptoms." (PMID 29068376, 2017). "Taraxacum officinale extracts (10 mg/kg) also protected rats from cholecystokinin-octapeptide-induced acute pancreatitis." (PMID 28077102, 2017). "Shirohara and Otsuki demonstrated that plasma CCK levels increased during acute pancreatitis, including gallstone pancreatitis, since edema of the bile duct causes transient disturbances in bile flow into the duodenum." (PMID 29068376, 2017). "In male Wistar rats, ZER suppressed cholecystokinin octapeptide- (CCK-8-) induced acute pancreatitis with significant reduction in serum amylase and lipase, cytosolic IL-6, iNOS, Mn- and Cu/Zn-SOD activities, and TNF-α concentration." (PMID 25025076, 2014). "The premature activation of the pancreatic digestive enzyme, trypsinogen to trypsin, in the pancreatic acinar cell is considered to be one of the main initiating events in acute pancreatitis; in this experimental model of acute pancreatitis, this required the CCK activation of PAK2." (PMID 40001881, 2025). "In addition, in the supramaximal CCK model as well as other models of acute pancreatitis, acinar cell death can occur and is mediated by the activation of apoptosis and necrosis." (PMID 40001881, 2025).
acute pancreatitis (continued). "Oral administration of P. scabiosaefolia can reduce the serum amylase and lipase levels in rats with cholecystokinin (CCK) octapeptide induced acute pancreatitis (AP), and inhibit the expression of proinflammatory cytokines to produce anti-inflammatory effects." (PMID 36733419, 2023). "Caerulein, a cholecystokinin analog, is known to induce acute pancreatitis in mouse models." (PMID 33255941, 2020). "Animal studies have shown that CCK and its receptors are initiating factors in acute pancreatitis." (PMID 31963306, 2020). "Similarly, administration of supraphysiologic concentrations of a cholecystokinin ortholog, cerulein, in mice resulted in acute pancreatitis and Prdm3 upregulation in murine acinar cells." (PMID 32179733, 2020). "Interestingly, REST ablation accelerated acute pancreatitis in mice treated with the cholecystokinin analog caerulein, as indicated by cellular morphology, elevated serum amylase levels and pancreatic edema." (PMID 32080178, 2020). "However, an abnormally high level of plasma CCK has been reported to occur in patients with chronic pancreatitis and acute pancreatitis." (PMID 31248019, 2019). "Thus, an acute obstruction increases circulating cholecystokinin levels that may be important in the very early pathogenesis of acute pancreatitis in post-ERCP and in biliary etiology." (PMID 40254129, 2026). "Acute pancreatitis induced by cerulein (CER), a cholecystokinin analog, was the most well‐characterized and widely used experimental model for acute edematous pancreatitis." (PMID 39415850, 2024). "Because it is impractical to know a priori whether a patient has a PanIN lesion during acute pancreatitis, a pancreas-specific KrasG12D mouse model was used, wherein PanIN lesions develop during acute pancreatitis induced by intra-abdominal injections of caerulein, a cholecystokinin analogue." (PMID 27009811, 2016). "On the other hand, supramaximal stimulation by a cholecystokinin analogue, cerulein, induced acute pancreatitis, the severity of which was not increased by preceding alcohol ingestion." (PMID 40254129, 2026). "Similar to that by cholecystokinin, hyperstimulation of pancreatic muscarinic receptors induces acute pancreatitis, which is also not exaggerated by preceding alcohol ingestion." (PMID 40254129, 2026). "Of note, miR-301a expression was no different in isolated acinar cells between PBS and cholecystokinin-8 treatment, which recapitulate necrosis of acute pancreatitis in vitro." (PMID 35211358, 2022). "In the present study, we investigated the relationship between the formation of endocytic vacuoles and Ca2+ influx developed in response to the inducers of acute pancreatitis [bile acid taurolithocholic acid 3-sulfate (TLC-S) and supramaximal concentration of cholecystokinin-8 (CCK)]." (PMID 25370603, 2015). "Besides, cholecystokinin (CCK), a major gastrointestinal hormone that plays an important role in stimulation of pancreatic secretion, has been revealed in high plasma level in patients with acute pancreatitis." (PMID 39403146, 2024).
Anorexia (38 papers, 2011 to 2026). Lack of desire to eat (loss of appetite). "GDF15 activates GFRALAP/NTS neurons and supports conditioned taste and place aversions, while the anorexia it causes can be blocked by a monoclonal antibody directed at GFRAL or by disrupting CCK neuronal signalling." (PMID 32723474, 2020). "Meanwhile, serum CCK level was found to be significantly higher in older individuals, and is suggested to contribute to aging-associated anorexia." (PMID 26700819, 2016). "Further evidence revealed that GDF15 signals via activation of cholecystokinin neurons in the area postrema and nucleus of the tractus solitarius may contribute to anorexia and body weight loss." (PMID 34925008, 2021). "Its major causes are an alteration in fundal compliance with an increase in antral stretch and enhanced cholecystokinin activity leading to increased satiation.This anorexia leads to weight loss in aging persons and is one of the component causes of the aging related sarcopenia." (PMID 28452130, 2017). "The suppression of CCK-induced anorexia by both PCPA and SB242084 strongly suggests that intact serotonergic signaling through 5-HT2C receptors is required." (PMID 41550979, 2026). "It is well known that exogenous administration of the satiety hormone cholecystokinin (CCK) produces robust anorexia in rodents and humans." (PMID 37349522, 2024). "The surgical completeness of the SDV was confirmed through multiple methods, encompassing resistance to CCK-8-induced anorexia, observed stomach enlargement, and retrograde neurotracing of the DMV using Fluorogold 47–49." (PMID 38228675, 2024). "High CCK levels are correlated with greater satiety after meals, thereby contributing to the anorexia of aging." (PMID 38892503, 2024). "Selective ablation of NTS NE neurons attenuates hypothalamic activation by cholecystokinin (CCK) while CCK-induced anorexia was also attenuated." (PMID 35330845, 2022). "We found that 1 and 2.5 mg/kg·bw of DON can acutely induce anorexia and increase the plasma intestinal hormones CCK, PYY, GIP, and GLP-1 in mice within 3 h." (PMID 34437383, 2021). "Increase in the concentration of CCK was more significant, which implied that its role in anorexia is more important." (PMID 34822552, 2021). "Although negatively correlated in this study, CCK is a satiety hormone and is involved in anorexia and nausea." (PMID 34055657, 2021). "In summary, this study found that DON can acutely induce anorexia in mice within 1–3 h, and it can also acutely increase the concentration of intestinal hormones CCK, PYY, GIP, and GLP-1 in mice plasma." (PMID 34437383, 2021). "The subthreshold dose of exenatide slightly reduced food intake alone and potentiated CCK-8-induced anorexia at 30 min." (PMID 33221554, 2021). "And despite the elevated plasma level, older adults maintained sensitivity to the satiating effects of exogenous CCK, suggesting that enhanced endogenous CCK activity should be responsible for the anorexia of aging." (PMID 32867089, 2020). "DON crosses the blood–brain barrier and targets the hypothalamus to produce anorexia behavior, and it affects the secretion of gut hormones, such as CCK, PYY, GLP-1, and 5-HT, which target the hypothalamus via the brain-gut axis to regulate appetite." (PMID 32878107, 2020). "In fact, a synergic effect between IL-1 and CCK inducing anorexia has been described, while IL-1 and GIP are factors that stimulate insulin release by the pancreas." (PMID 31191339, 2019). "While most peptides contribute to stress-induced anorexia (Ucns, CCK, and GLP-1), ghrelin can stimulate food intake under these conditions." (PMID 30210455, 2018). "In support, hypersensitivity to CCK has been reported in patients with functional dyspepsia and in healthy older people with anorexia of ageing." (PMID 30597915, 2018). "It is established that peripheral injection of cholecyctokinin (CCK-8) induces anorexia at least partly via vagal afferent nerve." (PMID 22184277, 2011).
Anorexia (continued). "Importantly, co-infusion of ICI 118,551 with CCK-8s notably attenuated the CCK-8s-induced anorexia (P < 0.05)." (PMID 41550979, 2026). "Generally, there seems to be an increased CCK secretion in the young anorexia patients." (PMID 40557463, 2025). "Moreover, intestinal CCK secretion has also been examined in patients suffering from eating disorders (anorexia nervosa, anorexia in the aging, and bulimia nervosa)." (PMID 40557463, 2025). "This is the first direct evidence that acute activity of OxtPVH neurons is required for the anorectic effects of exogenous CCK, though corroborates the complete blockade of CCK-induced anorexia recently reported after the ablation of oxytocin neurons with diptheria toxin." (PMID 39286269, 2024). "It has also been found that GFRAL is localized on cholecystokinin (CCK) positive neurons; GDF15 activates CCK neurons, and GDF15-induced anorexia is attenuated by CCK signaling blockade, suggesting that GDF15 is mediated by anorexigenic signaling in CCK neurons in the brainstem." (PMID 39050134, 2024). "DON can also induce the concentration of mouse plasma intestinal satiety hormones GLP-1, GIP, PYY, and CCK to rise rapidly within 2 h, while the intestinal anorectic hormone in mouse plasma returns to normal levels after 6 h, which is consistent with the anorexia before." (PMID 34437383, 2021). "However, some cases of anorexia occurring prior to the rise in the levels of CCK and GLP-1 have been reported, which suggests that other factors are involved in the process." (PMID 34822552, 2021). "Thus, we propose that the primary target for GDF15 is a distinct population of GFRAL/CCK neurons which span the AP/NTS to engage well-characterised circuitry involved in anorexia and conditioned aversion." (PMID 32723474, 2020). "In PD patients with anorexia, the plasma levels of CCK were elevated after eating." (PMID 31191339, 2019). "In this context, it has been shown that CCK and interleukin-1 (IL-1) may synergize to worsen anorexia and that TNF-α may interfere with the orexigenic effect of neuropeptide-Y (NPY)." (PMID 31191339, 2019). "In addition, DON and T-2 also induced the release of the satiety hormones, peptide YY (PYY) and cholecystokinin (CCK), which are critical mediators of anorexia." (PMID 29535978, 2018). "In an animal study, systemic administration of CCK was found to induce anorexia." (PMID 26700819, 2016). "While the present study did not investigate the anorexia of aging, the results regarding CCK-8 may be relevant to the risk of malnutrition in the elderly." (PMID 40005054, 2025). "Accordingly, in the chronic setting increased CCK release may contribute to the observed anorexia and loss of body weight at high altitude but not in the acute setting where CCK release is reduced." (PMID 22970220, 2012). "Aging also influences the levels of several hunger and satiety hormones, such as ghrelin, leptin, insulin, cholecystokinin (CCK), and peptide YY, which contribute to the anorexia of aging." (PMID 38892503, 2024). "Our previous findings suggest that DON and its four congeners 3-ADON, 15-ADON, NIV, FX induce anorexia in mice by regulating intestinal hormones including substance P (SP), glucagon-like peptide-17-36 amide (GLP-1), cholecystokinin (CCK)." (PMID 39691381, 2024). "Recent evidence points to an interaction between NTS and PBN neurons, including PBN-projecting noradrenergic NTS neurons mediating anorexia, and PBN-projecting CCK-expressing NTS neurons controlling feeding." (PMID 36588135, 2023). "This is in accordance with our previous research that DON selectively activated CaSR and elevated hormones CCK and PYY3–36 to mediate anorexia." (PMID 35737050, 2022). "Increases in CCK, GLP-1, and PYY are thought to be closely related to anorexia and therefore affect muscle, and this relationship has also observed in sarcopenia patients with liver cirrhosis." (PMID 35565864, 2022).
Anorexia (continued). "Direct injection of exogenous intestinal hormones CCK, PYY, GIP, and GLP-1 can trigger anorexia behavior in mice." (PMID 34437383, 2021). "Our findings here demonstrate that DON rapidly induces four intestinal hormones CCK, GLP-1, GIP, and PYY in the plasma of mice; the way this increase occurs is consistent with the induction of anorexia." (PMID 34437383, 2021). "We also proved that the intestinal hormones CCK, PYY, GIP, and GLP-1 can trigger anorexia behavior in mice, and the receptors of these hormones play an essential role in the antifeedant response induced by DON." (PMID 34437383, 2021). "In this species, DON also induces the release of the satiety hormones, peptide YY (PYY) and cholecystokinin (CCK), proposed as critical mediators of DON-induced anorexia." (PMID 24859243, 2014). "CCK-8s significantly suppressed feeding behavior (P < 0.05), and the concomitant infusion of yohimbine with CCK-8s did not significantly alter the CCK-8s-induced anorexia (P ≥ 0.05)." (PMID 41550979, 2026). "The co-infusion of 8-OH-DPAT with CCK-8s did not modify the CCK-8s-induced anorexia significantly (P ≥ 0.05)." (PMID 41550979, 2026). "In our experiments, Proglumide indeed suppressed both CCK- and DON-induced anorexia." (PMID 34437383, 2021). "Consequently, it seems most beneficial for future interventions to target CCK, leptin, PYY and insulin when investigating methods to augment energy intake to reduce the anorexia of ageing from an endocrine perspective." (PMID 31432431, 2020). "Again, the positive linear correlations found between CCK and IL-1, IL-1, and GIP, and GIP and insulin (other anorexigen) may perpetuate the anorexia and the insulin resistance suffered by our patients." (PMID 31191339, 2019). "In addition, bloating correlated with CgA (r = 0.85, P = 0.03), anorexia correlated with each of secretin (r = −0.91, P = 0.01) and GIP (r = −0.95, P=0.003), and nausea correlated with each of CCK (r= –0.89, P=0.01) and GIP (r= –0.95, P=0.003) in the idiopathic IBS subgroup." (PMID 34055657, 2021). "The elevated levels of CCK-8 observed in the current study group may suggest its post-natal role in the mechanisms leading to reduced food intake, even in groups that do not manifest the classic symptoms of the anorexia of aging." (PMID 40005054, 2025).